CCL2 (C-C motif chemokine ligand 2)
Diseases named in the same sentence as CCL2 in open-access papers (continued):
Sharing a sentence is not in itself a finding about the gene and the disease.
hypogonadism (3 papers, 2020 to 2023). A disorder characterized by decreased function of the gonads. "Overall, findings from Leydig cell work and mouse studies fit with clinical studies in which a reduction of serum levels of CCL2 is associated with improvement of diabetic conditions and recovery from hypogonadism in a cohort of infertile men having a history of metabolic syndrome." (PMID 35307018, 2022). "In this work, we used homozygous, leptin-resistant diabetic db/db mice that are characterized by hypogonadism, hyperglycemia, and testicular inflammation with increased IL-1β and chemokine (C–C motif) ligand 2 (CCL2)." (PMID 35307018, 2022). "Chemical inhibition of CCL2 protects murine and human Leydig cells from malfunction and apoptosis, it reverses the diabetic condition, and it ameliorates hypogonadism in the db/db mice." (PMID 35307018, 2022). "Together, these findings imply that genetic ablation of Ccl2 was capable of ameliorating hypogonadism in HED-fed mice." (PMID 33148888, 2020). "In a clinical cohort, the critical role of CCL2 in MetS-related hypogonadism was further supported by its significant correlations with testosterone and hypogonadism score." (PMID 33148888, 2020). "Moreover, after intervention, CCL2 levels were found to be not only highly and positively correlated with MetS components BMI, HOMA, and the proinflammatory factor sensitive C-reactive protein (sCRP) but also negatively correlated with hypogonadism indexes (testosterone and hypogonadism score)." (PMID 33148888, 2020).
idiopathic inflammatory myopathies (3 papers, 2012 to 2025). "Several inflammatory myopathies have been associated with CCL2, MCP-3 and RANTES, and CXCL12 and CCL2 have been shown to be increased in idiopathic inflammatory myopathies." (PMID 41348866, 2025).
immune deficiencies (3 papers, 2011 to 2019). "While overproduction of CCL2 leads to disease progression and severity in inflammatory related pathologies, underproduction leads to immune deficiencies in transgenic mice as demonstrated in CCL2 knockout mice challenged with S. pneumoniae." (PMID 21760952, 2011).
intracranial hemorrhage (3 papers, 2014 to 2023). Bleeding within the SKULL, including hemorrhages in the brain and the three membranes of MENINGES. "It was observed that CCL2 knockout could suppress microglia activation during the first 24 h in a rats model of intracranial hemorrhage, suggesting CCL2 was involved in acute microglia activation." (PMID 28870240, 2017). "Interestingly, in a model of intracranial hemorrhage, CCL2 knockout mice have reduced microglia activation only during the first 24 h, after which the levels are similar to wild-type mice." (PMID 25012628, 2014).
Japanese encephalitis (3 papers, 2012 to 2017). A disease due to a virus transmitted by an arthropod). "This is in contrast to observations in a Japanese encephalitis model, in which CCR2−/− mice had reduced monocyte infiltration while CCL2−/− mice had a paradoxical increase in this population in the brain." (PMID 29202854, 2017).
keratitis (3 papers, 2010 to 2018). A corneal disease that is characterized by inflammation of the cornea. "Viral DNA differentially stimulated IL-6 and CCL2 through Tlr9 and cytoplasmic DNA sensors, respectively, but by itself, viral DNA was insufficient to induce keratitis." (PMID 20419141, 2010). "CCL2 and CCL3 are critical to the recruitment of neutrophils in the context of keratitis." (PMID 29661181, 2018). "Injection of either of these concentrations failed to induce clinical keratitis, but did induce expression of CCL2 and a modest mononuclear cell infiltrate." (PMID 20419141, 2010).
kidney cancer (3 papers, 2007 to 2024). Primary or metastatic malignant neoplasm involving the kidney. "Thus, the CCL2/CCR2 signalling pathway emerges as a promising avenue for therapeutic exploration in the context of kidney cancer, warranting dedicated research." (PMID 39011666, 2024).
mastocytosis (3 papers, 2021 to 2023). A clonal myeloproliferative neoplasm characterized by the proliferation and accumulation of neoplastic mast cells in one or multiple organs or organ systems. "This was accompanied by changes in the gene expression of adhesion molecules including CD44 and other molecules known to be chemoattractant molecules and receptors for mast cells such as CXCR4 and CCL2 (or MCP-1) and with reported functions in mastocytosis." (PMID 37025992, 2023). "It was also found that CCL2 serum levels are significantly increased in mastocytosis patients compared with controls and higher in patients with advanced SM than in ISM." (PMID 33806685, 2021). "CCL2, produced by mast cells in addition to many other cell types and a chemoattractant for mast cells and mast cell progenitors was reported to be elevated in the serum of patients with aggressive mastocytosis, and the levels correlated with poor prognosis." (PMID 37025992, 2023). "Interestingly, it was shown that in children with mastocytosis, MCs may migrate to the skin and BM as the result of upregulation of CCL2/chemokine receptor 2 (CCR2) and vascular cell adhesion molecule (VCAM-1) and they may induce the expression/activation of transglutaminase 2 (TG2)." (PMID 33806685, 2021).
mental disorder (3 papers, 2009 to 2021). A disease that has its basis in the disruption of mental process. "In addition to cytokines, both CCL2 and PLAUR mRNA levels were found to be higher in non-obese patients with mental disorders." (PMID 30504920, 2018).
metastasis (3 papers, 2014 to 2025). The spread or migration of cancer cells from one part of the body (where they first appeared) to another. "One of these, IL1B, has been shown to increase CCL2 in follicular thyroid carcinoma, leading to lymph node metastasis." (PMID 25277206, 2014).
monocytopenia (3 papers, 2017 to 2025). "Fifth, the robust inhibition of monocyte infiltration in the neuron-specific CCL2-deficient mice argues explicitly that this chemokine drives trafficking to the brain while side-stepping all of the issues regarding monocytopenia that arise in CCL2−/− or CCR2−/− mice." (PMID 29202854, 2017).
muscular dystrophy (3 papers, 2019 to 2022). Muscular dystrophy (MD) refers to a group of more than 30 genetic diseases characterized by progressive weakness and degeneration of the skeletal muscles that control movement. "Our data showing elevated levels of several CC-motif-containing chemokines extend prior studies showing increased expression CCL2, CCL3, and CCL4 in muscle biopsies obtained from animal models and human patients suffering from muscular dystrophy or inflammatory myopathies." (PMID 33138863, 2020). "In our model of muscular dystrophy with miR-146a deficiency, the lack of similar differences in skeletal muscle may result from the higher miR-206 expression that was detected in miR-146a−/−mdx mice in comparison to mdx animals, as this microRNA was shown to directly diminish CCL2 expression." (PMID 31412923, 2019).
mycobacterial infection (3 papers, 2016 to 2024). "Furthermore, double knockdown of miR-126 and either cxcl12a or ccr2 reduced cell death and from miR-126 knockdown alone, demonstrating that the Cxcl12/Ccl2/Ccr2 signalling axis is driving the miR-126 knockdown-associated increase in ineffective macrophage recruitment to mycobacterial infection." (PMID 38307625, 2024). "We link infection-induced miR-126 to Tsc1 via activation of the mTOR pathway and improved macrophage function because of regulation of a Cxcl12/Ccl2/Ccr2 signalling axis during the early stages of mycobacterial infection." (PMID 38307625, 2024).
nasal polyps (3 papers, 2015 to 2023). "The macrophage-stimulating potential of CCL2 is correlated with COX-2 expression, which is, in turn, associated with the development of polypoid lesions, such as nasal polyps or colonic polyps." (PMID 37176721, 2023).
neurofibroma (3 papers, 2017 to 2024). An intraneural or extraneural neoplasm arising from nerve tissues and neural sheaths. "Ccl2 expression is up-regulated >80-fold on day 1 after nerve injury, decreasing to 6-fold at days 7 and 14, and remains up-regulated in neurofibroma (2.39x)." (PMID 28256556, 2017). "In addition, small-molecule-mediated inhibition of STAT3 signaling downregulated Ccl2/Ccl12 chemokines, which impaired neurofibroma macrophage populations." (PMID 36982554, 2023). "In neurofibroma, Tlr2 is slightly down-regulated (0.78x) in 7-month-old neurofibroma macrophages, and Ccl2 and Ccl3, which can increase Tlr2 expression, are not significantly up-regulated." (PMID 28256556, 2017).
non-Hodgkin lymphoma (3 papers, 2020 to 2025). Distinct from Hodgkin lymphoma both morphologically and biologically, non-Hodgkin lymphoma (NHL) is characterized by the absence of Reed-Sternberg cells, can occur at any age, and usually presents as a localized or generalized lymphadenopathy associated with fever and weight loss. "The CCL2 gene is overexpressed by non-Hodgkin lymphomas and multiple solid tumors." (PMID 35328046, 2022). "Moreover, CCL2 is overexpressed by a variety of hematological malignancy (non-Hodgkin lymphomas) and solid tumors as colorectal, pancreatic, gastric, prostate, and breast cancer in particular." (PMID 35328046, 2022). "In a study in 81 lymphoma patients, including 44 non-Hodgkin’s lymphoma (NHL), 37 Hodgkin’s lymphoma patients, and 20 healthy subjects as a control group, high serum levels of inflammatory markers, including CCL2, correlate with severity and low benefit from treatment." (PMID 33297571, 2020).
oligodendroglioma (3 papers, 2012 to 2023). A well-differentiated (WHO grade II), diffusely infiltrating neuroglial tumor, typically located in the cerebral hemispheres. "We did not observe differences in CCL2 protein levels between normal canine brain (n = 3) and high-grade canine oligodendroglioma (n = 6) samples (p = 0.381)." (PMID 37368789, 2023). "In our study, no specific genotype was associated with oligodendrogliomas exhibiting T2FMM, but PDGFRA and CCL2 were significantly upregulated among oligodendrogliomas without the sign, which likely reflects sampling bias of inclusion of more HGO in the group without the T2FMM sign." (PMID 37246729, 2023). "Using volcano plot analyses, 2 DEGs, PDGFRA and CCL2 were identified between dogs with and without the T2FMM, both of which were upregulated in dogs with oligodendrogliomas without the T2FMM." (PMID 37246729, 2023).
ovarian dysfunction (3 papers, 2018 to 2024). The inability of the ovaries to function. "However, whether FBXW7 directly targets CCL2 and CLU to mediate ovarian dysfunction is still unclear." (PMID 39031722, 2024).
papilloma (3 papers, 2012 to 2020). A benign epithelial neoplasm that projects above the surrounding epithelial surface and consists of villous or arborescent outgrowths of fibrovascular stroma. "The expression level of CCL2 was low in normal mucosa and hyperplasia, but continuously increased in the progression of pathological lesions including dysplasia, papilloma and carcinoma." (PMID 32103760, 2020).
pericarditis (3 papers, 2012 to 2024). An inflammatory process affecting the pericardium. "There have been some studies on CCL2, CD8A, and PTPRC in cardiovascular diseases; however, their roles in pericarditis require further research." (PMID 38455049, 2024).
pituitary tumour (3 papers, 2019 to 2023). "A study highlighted the potential angiogenic effect of CCL2 released by pituitary tumors, finding larger vessels in pituitary tumors secreting higher levels of CCL2." (PMID 37958702, 2023). "In addition to the pituitary tumour cell and immune cell-derived angiogenic compounds, secreted proteins from pituitary tumour-associated fibroblasts, namely CCL2 as previously shown, may further contribute for PitNET angiogenesis, as described in other cancers." (PMID 32946040, 2020). "Chemokines, such as CXCL8 (or interleukin (IL)-8), CCL2, CCL3, and CCL4, are secreted by pituitary tumors and non-tumor cells, such as macrophages, lymphocytes, or fibroblasts, and modulate the microenvironment composition." (PMID 37958702, 2023).
pleural tumor (3 papers, 2013 to 2018). "Here, using Evans’ blue pulse-and-chase, we show that CCL2/12 blockade is such a strategy to hamper enhanced extravasation in mice with pleural tumors." (PMID 23967166, 2013). "Furthermore, that during MPE formation, bone marrow-borne, splenic CD11b+Gr1+ cells are conditioned by solute mediators secreted by KRAS-mutant pleural tumours (possibly CCL2) and functionally contribute to MPE development." (PMID 28508873, 2017). "However, a qualitative impact of CCL2/12 blockade was evident: blood vessels within pleural tumors appeared smaller and less well-organized in chemokine-targeted animals, indicating retardation of neovascular assembly." (PMID 23967166, 2013). "CCL2 blockade yielded meaningful benefits, including significantly prolonged survival, as well as marked reductions in MPE incidence and volume, pleural tumor dissemination, and markers of pleural inflammation and vascular leakage." (PMID 23967166, 2013). "Immunodetection of murine F8A in A549 pleural tumors turned out similar with syngeneic studies: no intergroup difference in microvessel density was established, but neovessels appeared smaller and less organized in CCL2-targeted mice." (PMID 23967166, 2013). "In our hands, CCL2 and/or CCL12 neutralization did not alter pleural tumor dissemination and subcutaneous tumor growth." (PMID 23967166, 2013).
pleurisy (3 papers, 2019). Inflammation of the pleura. "In a murine model of pleurisy, the numbers of total mononuclear cells recruited to the pleural cavity were significantly decreased in both Plg−/− and Plg-RKT−/− mice, a response associated with decreased levels of the chemokine CCL2 in pleural exudates." (PMID 31316511, 2019).
pneumococcal pneumonia (3 papers, 2014 to 2023). A febrile disease caused by STREPTOCOCCUS PNEUMONIAE. "We also assessed BALF levels of other important pro-inflammatory mediators during pneumococcal pneumonia such as TNF-α, IL-6 and CCL2." (PMID 37275853, 2023).
polyp (3 papers, 2014 to 2021). A usually exophytic mass attached to the underlying tissue by a broad base or a thin stalk. "The polyp type had a significant impact on the fold change in CCL2, CCL7, and CCL8 expression." (PMID 34884259, 2021). "Therefore, this study was conducted to assess the suitability of MCP chemokines as targets for chemoprevention by determining the expression patterns of MCP-1/CCL2, MCP-2/CCL8, and MCP-3/CCL7 in colorectal polyps and the chemokine association with polyp potential for malignancy." (PMID 34884259, 2021). "The CCL2, CCL7, and CCL8 expression seemed to depend on the polyp location, as the lowest expression ratios were observed for the rectal polyps." (PMID 34884259, 2021). "The fold change in CCL2, CCL7, and CCL8 expression was significantly affected by the polyp size." (PMID 34884259, 2021). "This study was designed to determine the expression patterns of MCP-1/CCL2, MCP-2/CCL8, and MCP-3/CCL7 at the protein (immunohistochemistry; n = 62) and transcriptional levels (RTqPCR; n = 173) in colorectal polyps with reference to the polyp malignancy potential." (PMID 34884259, 2021). "The polyp expression of CCL2 and CCL8 (but not CCL7) was the lowest in the adenocarcinomas." (PMID 34884259, 2021). "Detailed analysis of the gene expression patterns in the normal mucosa and polyps showed that the CCL2, CCL7, and CCL8 expression in the normal tissue was comparable and not affected by the polyp type, contrary to gene expression in the polyps." (PMID 34884259, 2021).
psoriasis vulgaris (3 papers, 2018 to 2025). Plaque psoriasis is the most common presentation of psoriasis. "In the present study as well, GM-CSF and IL-4 enhanced OSM expression in isolated human monocytes, and there is a trend toward higher CCL2 expression in the skin lesions of AD and psoriasis vulgaris." (PMID 38035099, 2023).
Renal atrophy (3 papers, 2018 to 2023). Atrophy of the kidney. "We demonstrated that mice with global Ccl2 deficiency are protected from development of renal atrophy in RVH; we have not established whether Ccl2 signaling in parenchymal cells or in bone marrow derived infiltrating inflammatory cells is responsible for this protective effect." (PMID 29872089, 2018).
RSV bronchiolitis (3 papers, 2014 to 2021). "Among the most abundant chemokines in infants suffering from RSV bronchiolitis are CXCL10/IP-10, CXCL8/IL-8, CCL2/MCP-1 and CCL3/MIP-1α." (PMID 34320038, 2021).
septic peritonitis (3 papers, 2017 to 2024). Septic peritonitis is an inflammatory condition of the peritoneum that occurs secondary to microbial contamination. "In dogs with septic peritonitis, levels of the inflammatory cytokines C-C motif chemokine ligand 2 (CCL2) and interleukin 6 (IL-6) were significantly higher than in non-septic dogs, which contributes to migration and infiltration of macrophages into the area of insult." (PMID 33778035, 2021).
spina bifida (3 papers, 2022 to 2025). A congenital neural tube defect in which vertebrae are not fully formed. "Other mutant genes that are risk factors for spina bifida include the CCL2 gene." (PMID 35735913, 2022). "The CCL2 (MIM + 158105, C-C Motif Chemokine Ligand 2) −2518A>G promoter polymorphism has been associated with an increased risk for spina bifida in pregnant women who were homozygous for this variant." (PMID 41008661, 2025).
synucleinopathy (3 papers, 2022 to 2025). A neurodegenerative disease that is characterized by the abnormal accumulation of aggregates of alpha-synuclein protein in neurons, nerve fibers or glial cells. "Our observations at gene level, such as upregulation of chemokine and interferon response genes CCL2, IRF7, IL7R, and the immunomodulatory checkpoint gene VSIR, further reflect the complex immune environment within synucleinopathy appendixes." (PMID 41279937, 2025).
temporal lobe epilepsy (3 papers, 2015 to 2022). A localization-related (focal) form of epilepsy characterized by recurrent seizures that arise from foci within the temporal lobe, most commonly from its mesial aspect. "Other studies in patients with intractable temporal lobe epilepsy and rodents with induced seizures have demonstrated the upregulation of CCL2 in the hippocampus and other brain areas." (PMID 34512245, 2021). "CCL2 can also influence glia activation and the ensuing inflammation, which results in uncoupling of gap junctions between astrocytes and thus a reduced calcium buffering potential by the astrocytic network observed in temporal lobe epilepsy patients." (PMID 26133170, 2015). "Further highlighting the clinical relevance of these chemokines, elevated CCL2 protein was observed in the temporal lobe and hippocampus from patients with intractable epilepsy, and both CCL2 and CCL3 proteins were elevated in temporal lobe epilepsy patients measured with multiplex assay." (PMID 26133170, 2015).
Thiamine deficiency (3 papers, 2019 to 2025). Thiamine deficiency is a condition that occurs due to not enough thiamine (vitamin B1). "For example, the Ccl2-knockout mouse model protects the neuron from TD (thiamine deficiency)-induced cell death due to macrophage/microglial activation." (PMID 40019557, 2025). "Neuronal MCP-1/CCL2 induction during mild impairment of oxidative metabolism caused by microglial recruitment/activation exacerbated neurodegeneration in thiamine deficiency- (TD-) induced neuronal death." (PMID 34158806, 2021).
Tourette syndrome (3 papers, 2018 to 2025). A neurologic disorder caused by defective metabolism of the neurotransmitters in the brain. "An elevated expression of CCL2 (chemokine ligand 2), which is a chemokine that activates microglia, was also found in these brains, raising the question of whether the interneuron loss in Tourette syndrome is linked in some manner to microglia activation." (PMID 30096863, 2018).